MEAK7 (MTOR associated protein MEAK7)
Description:
Activates an alternative mTOR signaling pathway through RPS6KB2 activation and EIF4EBP1 repression to regulate cell proliferation and migration. Recruits MTOR at the lysosome, essential for MTOR signaling at the lysosome. Binds to the vacuolar-type ATPase (V-ATPase) complex, triggering a conformational change and is likely to regulate its activity. No effect on V-ATPase activity was observed in vitro in one study although it was suggested that it may have inhibitory activity in vivo. However, another study showed that it can promote V-ATPase activity. Protects neuronal cells against oxidative stress (By similarity).
Synonyms: KIAA1609; TLDC1; mEAK-7; EAK7
Tractability: Small molecule: a structure with a bound ligand is known. PROTAC: ubiquitination databases record sites on it.
Gene: Protein-coding gene on chromosome 16 (84,476,345 to 84,565,284, reverse strand). Ensembl gene ENSG00000140950.
Subcellular location: Membrane; Cytoplasm; Lysosome
Subcellular location (Human Protein Atlas): Cytosol; Nucleoli; Nucleoplasm
Gene Ontology:
Molecular function: protein binding
Biological process: positive regulation of protein localization to lysosome; regulation of cell migration; regulation of cell population proliferation; response to amino acid; response to insulin; response to nutrient levels; TOR signaling; response to oxidative stress
Cellular component: cytoplasm; cytosol; lysosomal membrane; lysosome; membrane; nucleus
Genetic constraint (gnomAD): Loss-of-function variants: 70 observed, 41.99 expected, observed/expected ratio (o/e) 1.67, 90% interval 1.37 to 1.93. The synonymous counts are far from expectation, so gnomAD's model fits this gene poorly and the ratio says little. Missense variants: 918 observed, 605.53 expected, observed/expected ratio (o/e) 1.52, 90% interval 1.43 to 1.6. Synonymous variants: 338 observed, 242.69 expected, observed/expected ratio (o/e) 1.39, 90% interval 1.27 to 1.52.
Homologues: Orthologues: chimpanzee MEAK7 (98% identical), macaque MEAK7 (95% identical), dog MEAK7 (78% identical), guinea pig MEAK7 (71% identical), rat Meak7 (66% identical), mouse Meak7 (65% identical), pig MEAK7 (63% identical), tropical clawed frog meak7 (50% identical), zebrafish meak7 (43% identical), Drosophila melanogaster CG5149 (30% identical), Caenorhabditis elegans eak-7 (22% identical). Paralogues in human: OXR1 (21% identical), NCOA7 (19% identical), TLDC2 (12% identical).
Diseases named in the same sentence as MEAK7 in open-access papers:
MEAK7 is named in the same sentence as 18 diseases in open-access papers, as found by Europe PMC text mining. Sharing a sentence is not in itself a finding about the gene and the disease. The quoted sentences say what the papers report.
lung carcinoma (3 papers, 2019 to 2022). "Because miR-1911-3p negatively regulated mEAK-7 expression and subsequent mTOR signaling, lung cancer cell proliferation and migration were analyzed in response to miR-1911-3p." (PMID 33364499, 2020). "MicroRNA-1911-3p; mEAK-7; mTOR signaling; Lung cancer; Cell proliferation; Cell migration; Cell biology; Gene expression; Gene regulation; Cancer research; Oncology." (PMID 33364499, 2020). "Through two different lung cancer studies, MEAK7 was found to be highly expressed in many NSCLCs and small cell lung carcinomas, when compared with normal lung tissue, suggesting that MEAK7 may play a role in lung tumorigenesis." (PMID 31288154, 2019).
breast carcinoma (2 papers, 2019 to 2026). "This study represents one of the initial comprehensive and multi-platform bioinformatic analyses demonstrating that MEAK7 exhibits elevated expression in breast cancer, particularly within the aggressive TNBC." (PMID 41972545, 2026). "For example, many prostate cancers exhibit MEAK7 deletions, whereas breast cancers often sustain substantial MEAK7 gene copy number amplification." (PMID 31288154, 2019). "As PI3K and mTOR signaling are crucial regulators of radiation resistance and self-renewal in many carcinomas, including cervical carcinoma, head and neck squamous cell carcinoma, and breast carcinoma, it is important to note that mEAK-7 is also a strong effector of these processes." (PMID 31288154, 2019).
non-small cell lung carcinoma (2 papers, 2019 to 2024). A group of at least three distinct histological types of lung cancer, including non-small cell squamous cell carcinoma, adenocarcinoma, and large cell carcinoma. "Recent studies have found that human MEAK7 mRNA is overexpressed in cancers such as hepatocellular carcinoma, lymph node-positive breast cancers, and non-small-cell lung cancer." (PMID 38532930, 2024). "Structural and functional analyses conducted in both physiological and pathophysiological conditions suggest mEAK-7 could serve as a promising therapeutic target against tumors, particularly non-small-cell lung cancer." (PMID 38532930, 2024).
acute myeloid leukemia (1 paper, 2019). Acute myeloid leukemia (AML) is a group of neoplasms arising from precursor cells committed to the myeloid cell-line differentiation. "Patients who died from ductal breast carcinoma (p = 2.72 × 10−6, Fold Change: 2.136) and acute myeloid leukemia (p = 7.99 × 10−5, Fold Change: 2.655) had enhanced MEAK7 expression." (PMID 31288154, 2019).
hepatocellular carcinoma (1 paper, 2024). A malignant tumor that arises from hepatocytes. "Multiple studies have revealed increased mRNA levels of human MEAK7 in tumors, including hepatocellular carcinoma and lymph node-positive breast cancers." (PMID 39796034, 2024). "The examination of the function of Mammalian Enhancer-of-Akt-1-7 (mEAK-7) in mTORC1 signaling reveals that S6K2 promotes cell proliferation and migration in response to mTOR activation in various cancer types, such as hepatocellular carcinoma and lymph node-positive breast cancers." (PMID 39796034, 2024).
laryngeal carcinoma (1 paper, 2019). Carcinoma that arises from the laryngeal epithelium. "In a screen of human squamous cell carcinomas, the UM-SCC-17A cell line, derived from the primary laryngeal cancer site of a 48-year-old female patient, did not express detectable levels of mEAK-7 protein." (PMID 31288154, 2019).
lung adenocarcinoma (1 paper, 2019). A carcinoma that arises from the lung and is characterized by the presence of malignant glandular epithelial cells. "As Oncomine databases demonstrate that higher MEAK7 expression is associated with poor patient prognoses, we sought to investigate this via a lung adenocarcinoma tissue microarray detailing patient survival data." (PMID 31288154, 2019).
metastatic cancer (1 paper, 2019). A carcinoma which has spread from the original site of growth to another anatomic site. "We determined that there are high mEAK-7 protein levels in the tumors and lymph nodes of patients with metastatic cancer, that mEAK-7high patients have poor prognoses, and that mEAK-7 is essential for self-renewal and radioresistance." (PMID 31288154, 2019).
cancer (7 papers, 2019 to 2025). A tumor composed of atypical neoplastic, often pleomorphic cells that invade other tissues. "Genetic modifications to MEAK7 included deletions, copy number amplifications, and mutations; yet these modifications were found to be cancer type dependent." (PMID 31288154, 2019). "Also, an association was found between MEAK7 expression and outcomes of patients with cancer." (PMID 31288154, 2019). "This implies the tumor-suppressive role of miR-1911-3p in modulating mTOR signaling by regulating mEAK7 in human cancers." (PMID 39770519, 2024). "Here, we summarize the current known roles of mEAK-7 in normal physiology and cancer development by reviewing the latest studies and discuss potential future developments of mEAK-7 in targeted cancer therapy." (PMID 38532930, 2024). "Collectively, these studies provide a novel perspective towards developing a cancer treatment targeting mEAK-7-associated mTOR signaling in NSCLC and other malignancies exhibiting elevated mEAK-7 expression." (PMID 38532930, 2024). "Here, we present a concise overview of the latest significant discoveries concerning the physiological roles of mEAK-7 and current understanding in the context of carcinogenesis and the advancement of cancer." (PMID 38532930, 2024). "Heightened mRNA expression levels of mEAK-7 have been observed in several cancer cell lines and there is significant elevation of both mEAK-7 and mTOR signaling in tumor and metastatic lymph nodes of patients diagnosed with NSCLC." (PMID 38532930, 2024). "Dysregulation of mTOR signaling fosters cancer development through a myriad of events, including the involvement of Mammalian Enhancer-of-Akt-1-7 (mEAK-7), which activates alternative mTOR signaling." (PMID 39796034, 2024). "mEAK-7 is expressed predominantly in metastatic human cancer and forms a novel mTOR complex involving DNA-PK to promote S6K2 signaling and suppress 4E-BP1." (PMID 33364499, 2020). "To identify MEAK7 genomic alterations in human patients with cancer, we accessed the cBioPortal database." (PMID 31288154, 2019). "The CD44+/CD90+ cell population expressed n-cadherin, which is known as an essential component of the epithelial-mesenchymal transition state in CSCs and suggests that high levels of mEAK-7 in cancer cells are more likely to metastasize." (PMID 31288154, 2019). "mEAK-7 (mammalian EAK-7 or MTOR-associated protein, eak-7 homolog), is an evolutionarily conserved lysosomal membrane protein that is highly expressed in several cancer cells." (PMID 38532930, 2024). "Likewise, mEAK-7 has been shown to be an essential effector of cell proliferation and migration in human cancer cells." (PMID 33364499, 2020). "In this study, we hypothesized that miRNAs regulate mEAK-7 to modify mTOR signaling in cancer cells." (PMID 33364499, 2020). "Thus, miR-1911-3p functions as a suppressor of mTOR signaling through the regulation of MEAK7 mRNA translation in human cancer cells." (PMID 33364499, 2020). "Although CD44+/CD90+ cells demonstrate radiation resistance and self-renewal capacity that correlate with elevated mEAK-7 protein levels, loss of mEAK-7 alone does not result in enhanced cell apoptosis in human cancer cells." (PMID 31288154, 2019). "Upregulation of Noxa occurs in response to DNA damage after mEAK-7 knockdown, which ultimately leads to cellular apoptosis, suggesting that mEAK-7 plays a role in the DNA damage response and cancer cell survival." (PMID 31288154, 2019). "However, the precise molecular mechanisms and signal transduction pathways of mEAK-7 in cancer remain largely unknown, motivating the need for further investigation." (PMID 38532930, 2024). "Multiple recent studies have identified mEAK-7 as a positive activator of mTOR (mammalian/mechanistic target of rapamycin) signaling via an alternative mTOR complex, implying that mEAK-7 plays an important role in the promotion of cancer proliferation and migration." (PMID 38532930, 2024).
cancer (continued). "However, despite recent findings, the precise molecular mechanisms and signal transduction pathways controlled by mEAK-7 in cancer remain largely unknown, with in vivo investigations yet to be systematically explored." (PMID 38532930, 2024). "It is well known that aberrant mTOR signaling results in diverse diseases such as diabetes type II, neurological disorders, and cancer, and thus a more complete understanding of the interactions of mTOR and mEAK-7 may be important to preventing or treating these human conditions." (PMID 33364499, 2020). "Thus the MEAK7 expression profile of patients with cancer may provide insight into predicting patient prognosis and survival." (PMID 31288154, 2019). "Thus, mEAK-7 protein and activated mTOR signaling was found to be enhanced in primary NSCLC, and substantially detected in metastasized lymph nodes, suggesting that mEAK-7 could function as a biomarker for patients with metastasized cancers." (PMID 31288154, 2019). "For now, mTORC3 contains ETV7 and other undefined components, while mTORC4 includes mEAK7 and DNA-PKcs, which are hypothesized to play roles in tumorigenesis and anti-cancer drug resistance by controlling T cell’s response to DNA damage and cancer cell physiology." (PMID 39273395, 2024). "This evidence, combined with our findings that mTOR signaling, mEAK-7, and S6K2 are upregulated in CD44+/CD90+ cancer cell populations, suggests that mEAK-7 is involved in mTOR signaling in CSCs." (PMID 31288154, 2019). "However, the role of mEAK-7 in human cancers has not been determined, and the downstream regulation of mEAK-7 in human cells is still unclear." (PMID 41262242, 2025). "Interestingly, while mEAK-7 protein is predominantly detected in human cancer cell lines, it is not consistently expressed in all cancers." (PMID 33364499, 2020). "Although mEAK-7 protein levels appear to be disproportionately high in human cancer cell lines when compared with non-cancerous cells, this limited observation does not exclude the possibility that mEAK-7 is present in healthy human tissues, because mTOR expression is found in many tissue types." (PMID 31288154, 2019). "However, the role of mEAK-7 in human cancer has not yet been identified." (PMID 31288154, 2019).
tumor (4 papers, 2019 to 2026). "mEAK-7 and (Ser240/244) p-S6 protein levels were significantly elevated in the primary human tumor when compared with the normal adjacent tissue." (PMID 31288154, 2019). "Multivariate Cox regression identified MEAK7 as a significant prognostic factor for overall survival, independent of age and tumor stage." (PMID 41972545, 2026).
MEAK7 also shares sentences with these, for which no sentence is quoted: autism (1 paper); cervical carcinoma (1); ductal breast carcinoma (1); head and neck squamous cell carcinoma (1); pancreatic cancer (1); prostate carcinoma (1); small cell lung carcinoma (1); squamous cell carcinoma (1).